EGFR (epidermal growth factor receptor)
Diseases named in the same sentence as EGFR in open-access papers (continued):
Sharing a sentence is not in itself a finding about the gene and the disease.
tumor (continued). "Clinicopathological analysis showed that high ADORA2B expression has significantly reverse correlation with four important clinical parameters, ER positivity (P < 0.01), PgR positivity (P = 0.027), EGFR positivity (P < 0.01) and tumor size (P = 0.037), but not HER-2 positivity (P = 0.77)." (PMID 30349649, 2018). "In our study, tumor viability and proliferation at day 7 did not significantly relate to stage of disease, tumor site, the abundance of cancer cells at day 0 or the percentage of EGFR expression." (PMID 29861851, 2018). "NK cells play a crucial role in tumor immunosurveillance with a unique capacity of killing cancer cells via antibody dependent cellular cytotoxicity (ADCC), particularly in the setting of head and neck cancer (HNC) where cetuximab, an EGFR-specific mAb, has been used since 2006." (PMID 30400822, 2018). "Indeed, RN765C showed potent in vitro cell killing activity in EGFR high tumor cell lines, even in those that were non-responsive to cetuximab." (PMID 30323890, 2018). "Furthermore, in our xenograft model, EGFR-targeted monotherapy failed to prevent tumor recurrence, whereas the pan-ERBB inhibitor dacomitinib suppressed tumor growth." (PMID 30044378, 2018). "Furthermore, EGFR and HER-2 have been revealed to play a significant role in metastasis to the bone marrow, and these factors exhibited elevated activity in tumour initiating cells (TICs) and circulating tumour cells (CTCs)." (PMID 30134822, 2018). "miRNA 200 family targets ZEBs and regulates negative tumor development and EMT, whole-genome miRNA analysis of GBM shows that loss of miRNA200c expression is related with EGF receptor (EGFR) amplification and ZEB1 overexpression, suggesting the involvement of ZEB1 in tumor aggressiveness." (PMID 29642503, 2018). "Importantly, combined administration of trametinib and EGF also facilitated an apoptotic switch in EGFR-transformed primary tumor cells, but not normal mammary epithelial cells." (PMID 30250119, 2018). "However, EGFR amplification and rearrangement were observed throughout the tumor, including regions with no EGFRvIII expression, thus indicating that specific mechanisms modulate EGFRvIII expression, even in the presence of high gene amplification." (PMID 30279357, 2018). "Certain tumor sub-clones may harbor resistance to anti-EGFR therapy, and might be present in only a small fraction of the overall tumor mass, rendering them non-detectable by conventional PCR." (PMID 30234115, 2018). "However, mechanisms for corticotroph-specific tumor induction by EGFR or for EGFR upregulation of ACTH/POMC expression have not been clearly elucidated." (PMID 30147673, 2018). "Median DpR was also better in the chemotherapy plus anti EGFR mAb versus the chemotherapy plus bevacizumab irrespective of tumor locations (FIRE-3 42.0% vs 30.8% for left-sided; 25.8% vs 17.7% for right-sided; PEAK 70% vs 48% for left-sided, 50% vs 45% for right-sided)." (PMID 30296945, 2018). "We also show that the binding capability of the TM in combination with the density of EGFR on the tumor cell decides whether or not UniCAR T cells will attack the target cell." (PMID 29876011, 2018). "Interestingly, the antibodies did not provide further benefits even when they were used together with MIT, implying that PC3 tumours grow in a largely EGF/EGFR axis-independent manner in the absence of surrounding stromal cells." (PMID 30333494, 2018). "In addition, EGFR recycling may be affected or changes in EGFR signaling may impact the PI3K-AKT-mTOR cascade and thus tumor growth and survival." (PMID 29303993, 2018). "However, considerable evidence has demonstrated that EGFR blockade, or inhibition of other receptor systems such as HER2, MET and IGF-IR leads to enhanced or re-activated STAT3 activity and subsequent continued tumor progression." (PMID 30572654, 2018). "However, there was no reduced uptake of 64Cu-PCTA-cetuximab in TE-4 tumor with intermediate EGFR expression by cetuximab treatment." (PMID 30373221, 2018).
tumor (continued). "In vitro and in vivo studies indicated that the expression of mir-24-3p enhanced tumor growth, invasion into local tissues, metastasis to lung tissues and decreased overall mouse survival by direct targeting PTPN0 and PTPRF and therefore downregulating phosphorylation levels of EGFR." (PMID 29560116, 2018). "Therefore, in addition to altering EGFR activity, ALIX KD may also affect the quality and composition of exosomes, with downstream consequences for tumor biology." (PMID 30021161, 2018). "These functional proteins are involved in tumor metastasis, angiogenesis, membrane fusion, cytokine and growth factor shedding and cell migration as well as processes such as fertilization, neurogenesis, myogenesis, embryonic TGF-α and epidermal growth factor receptor (EGFR) release and signaling." (PMID 29393911, 2018). "Furthermore, we demonstrated that miR-548k modulating the tumor microenvironment by promoting VEGFC secretion and stimulating lymphangiogenesis through ADAMTS1/VEGFC/VEGFR3 pathways, while promoting metastasis by regulating KLF10/EGFR axis." (PMID 30131072, 2018). "Additionally, the analysis of E-cadherin expression was performed in order to compare our method with the previously published studies, and the distribution of EGFR and HER2 gene amplifications were examined among these subgroups in the intestinal-type tumours." (PMID 29046940, 2018). "The two highly EGFR-amplified cases also contained high-level focal amplicons targeting other well-known oncogenic pathways, suggesting that additional co-occurring genomic lesions may contribute to PD-L1 overexpression in TNBC tumor cells." (PMID 29996881, 2018). "Recent studies have shown that the efficacy of immune checkpoint inhibitors in EGFR-mutant NSCLC patients is not satisfactory, which might be caused by low PD-L1 expression, inhibitory immune microenvironment and low tumor mutation load." (PMID 30172273, 2018). "Together, these data demonstrate that constitutive activation of ERBB4 (through mutation or ligand stimulation) promotes GBM cell growth and that, following anti-EGFR treatment, ERBB4 activation may result in increased tumor growth by upregulating ERK activity." (PMID 30044378, 2018). "No evaluation of downstream phosphorylation events in the tumor tissue was included in this analysis, still these results suggest that tumors with high EGFR signaling activity and intact signal transduction are sensitive to EGFR inhibitors." (PMID 30129426, 2018). "In addition, EGFR and KDR genes were over-expressed in the tumor tissue." (PMID 29324814, 2018). "The mechanism of how this tumor-suppressive role of EGFR works is not known." (PMID 29904166, 2018). "We identified seven oncogenes (NRAS, EGFR, RXRA, HRAS, KRAS, AKT1, ERBB2; q<0.10) and seven putative tumor suppressor genes (ARID1A, TXNIP, CTNNB1, PIK3RI, CDKN2A, KLF5, STAG2; q<0.10) significantly regulated between tumor and control, which were formerly reported to be altered in BC." (PMID 30419021, 2018). "Also during the last decade, a number of genetic alterations have been described in NSCLC, being Kristen Rat Sarcoma viral oncogene (KRAS), Epidermal Growth Factor Receptor (EGFR) and Anaplastic Lymphoma Kinase (ALK) the most commonly altered oncogenes acting as tumor genomic drivers." (PMID 29455666, 2018). "Thanks to next generation sequencing (NGS) and circulating tumor DNA (ctDNA) studies, the authors also showed the mechanisms of resistance to anti-EGFR drugs, such as the presence of EGF-R negative tumor clones, KRAS mutation/amplifications, PTEN deletion, and NRAS/HER2/MYC amplifications." (PMID 30205505, 2018).
tumor (continued). "Similarly, EGFR pathway activation has been found to be correlated with development of immunosuppressive microenvironment represented by upregulation of PD-1, PD-L1, CTLA-4, and multiple tumor-promoting inflammatory cytokines." (PMID 30294272, 2018). "Mechanisms by which TAMs facilitate intravasation of tumor cells are mediated via molecular interactions that involve for example a paracrine loop in which epidermal growth factor (EGF), produced by TAMs, increases the invasiveness and migration of cancer cells expressing the EGF receptor (EGFR)." (PMID 29584702, 2018). "On the other hand, the effect of cetuximab administration in CRC patients might result in a lower therapeutic effect on the primary tumor due to the presence in situ, as we have shown by immunochemistry, of TAF that express EGFR and can subtract the antibody, thus reducing its availability." (PMID 29910806, 2018). "Four of the five upregulated RMGs (CTNNB1, EGFR, NRAS, and KIT) were oncogenes and 12 of the 32 downregulated RMGs were tumor suppressor genes, which was consistent with the increased expression of oncogenes and decreased expression of tumor suppressor genes in tumor development." (PMID 30107644, 2018). "Tumor dynamics obtained from KRAS monitoring could provide important information about treatment strategies for patients with mCRC, such as detection of drug resistance to anti-EGFR antibody before radiographic documentation of disease progression." (PMID 29849949, 2018). "Furthermore, EGFR-dependent increase of apoptosis of tumour cells was independent of the sterical configuration of the molecule, i.e., the position of scTRAIL in the IgG molecule, as shown by competition with cetuximab." (PMID 29773864, 2018). "Indeed, we and others have demonstrated that blocking one receptor is not sufficient in inhibiting STAT3 activity, as other uninhibited pathways such as those driven by EGFR, IL-6R and IL-11R can reactivate STAT3, leading to continued tumor growth and refractory outcomes clinically." (PMID 30572654, 2018). "Furthermore, it has been reported that antibodies recognizing multiple epitopes of epidermal growth factor receptor (EGFR) were able to induce complement-dependent tumor cell killing while a monoclonal antibody was not." (PMID 30034625, 2018). "In the past 10 years, we and other laboratories have shown that anti-EGFR, anti-HER2, anti-CD20, and anti-CD47 in combination with immune checkpoint blockade could have synergistic effects in host adaptive anti-immune responses and tumor eradication." (PMID 30533489, 2018). "Nevertheless, it is plausible that the potent anti-stemness effects observed by targeting EGFR, IGFR, and PDGFR pathways could also be due to a direct effect on the tumor cells, since these signaling pathways are frequently altered in different cancers, including HNSCC." (PMID 30227608, 2018). "The aim of this study was to describe overall survival (OS) with current first-line treatment for patients presenting with stage IV NSCLC without known EGFR or ALK tumor aberrations across a broad range of community oncology practices in the United States (US)." (PMID 28644837, 2017). "The individual response to NAC appears to be mostly dependent on the tumor molecular profile: tumors lacking hormone receptors are more sensitive to cytotoxic chemotherapy, and, within triple-negative tumors, those overexpressing EGFR are the most responsive." (PMID 29267323, 2017). "Irrespective of EGFR or IDH status or the observed heterogeneity of ZEB1 in the parental tumor, ZEB1 was homogeneously expressed in virtually all cells of all four cell lines, which could be quantified by image cytometry." (PMID 28945795, 2017). "In former studies, we tested polyplexes with an EGFR-specific targeting peptide (GE11) as NIS gene delivery vehicles in a subcutaneous HuH7 xenograft tumor model as well as in orthotopic pancreatic ductal adenocarcinoma, which resulted in high tumor-specific NIS-mediated iodide accumulation." (PMID 29190908, 2017).
tumor (continued). "At present mCRC patients are selected for anti-EGFR mAb therapy provided their tumours do not harbour any RAS mutations, as no clear associations have yet been found between the expression of EGFR protein determined by immunohistochemistry and response to these inhibitors." (PMID 28032593, 2017). "Overall, the current data show multiple targets of ZR30 for its tumor suppressive effect, including membrane receptors (EGFR, NOTCH1) and their downstream AKT-signaling, pro-invasive and pro-angiogenic extracellular protease (MMP2), and oncogenic transcription factor (FOXM1)." (PMID 29290950, 2017). "It is uncertain whether PTL is just a negative prognostic indicator reflecting tumor biology irrespective of treatment or is a genuine predictive marker of the response to anti-EGFR treatment." (PMID 29169325, 2017). "When it comes to targeted drugs directed specifically towards the tumour cells in CRC, the EGFR antibodies cetuximab and panitumumab are now often routinely added to the chemotherapy in advanced CRC, if the tumour cells are not harboring any KRAS or BRAF mutation." (PMID 29262612, 2017). "Immunohistochemistric analysis revealed that the percentages of EGFR+ or KI67+ cells and the levels of HIF-1α expression and microvessel density (MVD) in the XWLC-05-miR-370 tumor sections were significantly lower than that in the XWLC-05-miR-NC tumor sections." (PMID 29152147, 2017). "The epidermal growth factor receptor (EGFR) and vascular endothelial growth factor receptor (VEGFR-2), as potent targets for cancer therapy, have been proved to be crucial in signal transduction pathways involved in tumor cell proliferation, differentiation, migration and angiogenesis." (PMID 29295519, 2017). "In tumors lacking EGFR expression, response to the targeted drug was unexpected, while in tumors with an EGFR overexpression, the accessibility of the tumor was hypothesized to be a determining factor in drug uptake." (PMID 27965472, 2017). "Furthermore, hypoxia can lead to increased metastasis, at least in certain tumor cell types, thus inhibiting the EGF/EGFR/arginase II pathway may also potentially have an additional benefit in limiting metastasis." (PMID 28330951, 2017). "In the current study, we examined EGFR mutant cell lines, including gefitinib-resistant PC9 cell lines, for the effect of afatinib in combination with TPCA-1, in inhibiting tumor growth proliferation and influencing signaling pathways that could down regulate STAT3." (PMID 28521301, 2017). "Moreover, microvesicles containing EGFRvIII are found to merge with the plasma membranes of cancer cells lacking this type of receptor and the share of EGFR mutants between cancer cells promote tumour development." (PMID 28393839, 2017). "Numerous findings have suggested that a substantial portion of the effects attributed to EGFR antagonist treatment might not be based on direct influence on the tumor itself." (PMID 28970798, 2017). "Interestingly, in one patient we observed that while there was no detectable expression of EGFR in the primary tumour, the liver metastasis from the same patient was strongly positive for EGFRvIII expression (Data not shown)." (PMID 28032593, 2017). "For example, Ets21C is a known downstream target of JNK signaling in wound healing, and EGFR signaling in the intestinal stem cells, and is also required as a co-factor for the JNK pathway transcription factor AP-1 in regulating transcriptional targets during tumor formation." (PMID 28753614, 2017). "Even though the use of EGFR inhibitors is considered “off-label” in EC, knowing whether or not the tumor expresses EGFR is crucial when prescribing tyrosine kinase inhibitors." (PMID 28421164, 2017).
tumor (continued). "The partial inhibition in tumor growth observed with JNJ-61186372-IgG2σ and the c-Met monovalent antibody was proposed to be due to inhibition of c-Met signaling as the in vitro data and in vivo H1975 model data presented here suggest that the EGFR arm drives the Fc effector mechanism." (PMID 27786612, 2017). "Variant III of the epidermal growth factor receptor (EGFRvIII), the most common variant of EGFR first identified in human GBM, is also present in many other tumor types, but is not found in healthy tissues, which makes EGFRvIII a suitable target for CAR-T cell therapy." (PMID 28466386, 2017). "In a tumor model driven by both EGFR and c-Met, treatment with Fc-silent JNJ-61186372 or with c-Met single-arm antibody reduced tumor growth inhibition compared to treatment with JNJ-61186372, suggesting that the Fc function of JNJ-61186372 is essential for maximal tumor inhibition." (PMID 27786612, 2017). "Tumor cell-specific expression of EGFR may explain why TMEM16A overexpression promotes proliferation in many tumors expressing EGFR, but not in HEK293 cells." (PMID 28893247, 2017). "Additionally, during in vitro culture, several genomic aberrations, e.g. amplification of EGFR, which are present in the primary tumor, are not maintained." (PMID 28183348, 2017). "Finally, we monitored whether changes in EGFR dynamics affect ADCC responses and tumor cell growth inhibition." (PMID 28467975, 2017). "So far, the development of targeted therapies was mostly fueled by knowledge related to primary tumor biology and, currently, around one dozen therapeutic antibodies and 28 different inhibitors are in clinical application, targeting essentially the tumor antigens HER2, EGFR, EpCAM, BRAF and VEGF." (PMID 27683128, 2017). "Moreover, in tumor cells, Met is able to bind EGFR and to be phosphorylated without an upstream HGF activation." (PMID 28446239, 2017). "However, the COG and TRANS-COG trials demonstrated that the tumor response to EGFR-TKI correlates with EGFR status rather than histological subtypes." (PMID 28881608, 2017). "However, surprisingly, EGFR ubiquitylation and phosphorylation, as well as tumor growth rates were not significantly affected by Cbl overexpression." (PMID 29268862, 2017). "Although EGFR inhibition by various inhibitors may not be curative in solid tumors, combination approach with radiotherapy might moderately improve local tumor control." (PMID 29190900, 2017). "The NCCN guidelines state that all patients with metastatic CRC should have tumor tissue genotyped for KRAS, NRAS, and BRAF mutations, and patients with any known KRAS or NRAS mutation should not be treated with anti-EGFR therapy such as cetuximab and panitumumab." (PMID 29212173, 2017). "A limitation of this kind of analysis and a possible explanation for this remarkable result is that EGFR expression was only determined for one sample which might not represent the whole tumor." (PMID 27965472, 2017). "In addition, EGFR, Mucin-1 (MUC1), and integrin beta-4 (ITGB4), which promote tumor growth and metastasis, may be bad prognostic factors in this tumor." (PMID 29282096, 2017). "Since previously direct effects of SATB1 on HER2 have been shown, one explanation for this discrepancy may be mutual effects of one HER receptor (here: EGFR) on the expression of other family members (here: HER2), as found in other tumor entities (Gutsch and Aigner, unpublished)." (PMID 28049521, 2017). "In addition to canonical NF-κB pathways, STAT1, STAT3, JUN, EGFR, and CEBPB were also on the top list, and these proteins may play crucial roles in tumour-induced DC signal transduction." (PMID 28350008, 2017). "The presence of EGFR gene mutations and, in particular, ALK gene rearrangement could be associated with the lack of PD-L1 expression on tumor cells." (PMID 28969070, 2017).